ASPA (aspartoacylase)
Description:
Catalyzes the deacetylation of N-acetylaspartic acid (NAA) to produce acetate and L-aspartate. NAA occurs in high concentration in brain and its hydrolysis NAA plays a significant part in the maintenance of intact white matter. In other tissues it acts as a scavenger of NAA from body fluids.
Synonyms: ACY2; ASP
Tractability: Small molecule: a structure with a bound ligand is known; it has a high-quality binding pocket.
Gene: Protein-coding gene on chromosome 17 (3,472,374 to 3,503,405, forward strand). Ensembl gene ENSG00000108381.
Subcellular location: Cytoplasm; Nucleus
Subcellular location (Human Protein Atlas): Cytosol
Pathways (Reactome):
Metabolism: Aspartate and asparagine metabolism
Gene Ontology:
Molecular function: aspartoacylase activity; identical protein binding; protein binding; hydrolase activity, acting on carbon-nitrogen (but not peptide) bonds, in linear amides; hydrolase activity, acting on ester bonds
Biological process: acetate metabolic process; aspartate biosynthetic process; aspartate metabolic process
Cellular component: cytosol; cytoplasm; nucleus; myelin sheath
Genetic constraint (gnomAD): Loss-of-function variants: 17 observed, 23.22 expected, observed/expected ratio (o/e) 0.73, 90% interval 0.5 to 1.1. The upper end of that interval is the gene's LOEUF score, 1.1, which puts it in group 4 of 6, group 1 being the genes least tolerant of losing a copy. Missense variants: 315 observed, 381.82 expected, observed/expected ratio (o/e) 0.82, 90% interval 0.75 to 0.91. Synonymous variants: 124 observed, 131.87 expected, observed/expected ratio (o/e) 0.94, 90% interval 0.81 to 1.09.
Gene-disease validity (ClinGen):
ClinGen rates the evidence that ASPA causes each of these diseases.
Canavan disease (autosomal recessive): Definitive. A neurodegenerative disorder; its spectrum varies between severe forms with leukodystrophy, macrocephaly and severe developmental delay, and a very rare mild/juvenile form characterized by mild developmental delay.
Homologues: Orthologues: chimpanzee ASPA (100% identical), macaque ASPA (97% identical), pig ASPA (92% identical), rabbit ASPA (91% identical), dog ASPA (90% identical), guinea pig ASPA (88% identical), mouse Aspa (86% identical), rat Aspa (70% identical), tropical clawed frog aspa (63% identical), zebrafish aspa (61% identical). Paralogues in human: ACY3 (44% identical).
Diseases named in the same sentence as ASPA in open-access papers:
ASPA is named in the same sentence as 56 diseases in open-access papers, as found by Europe PMC text mining. Sharing a sentence is not in itself a finding about the gene and the disease. The quoted sentences say what the papers report.
Canavan disease (67 papers, 2008 to 2025). "Canavan's disease is a neurodegenerative spongiform leukodystrophy resulting from a mutation of the aspartoacylase-encoding gene." (PMID 41458849, 2025). "Canavan disease (CD) is caused by biallelic pathogenic variants in ASPA which encodes the oligodendrocyte-specific enzyme aspartoacylase, responsible for hydrolyzing N-acetylaspartic acid (NAA) into acetate and aspartate." (PMID 41315317, 2025). "Canavan disease (CD) is a rare autosomal recessive leukodystrophy caused by biallelic pathogenic variants in the ASPA gene." (PMID 40257001, 2025). "In conclusion, this description of a rare congenital spongiform leukodystrophy in the German Shepherd breed, closely resembling to Canavan disease in humans, is likely caused by a genetic alteration unrelated to the ASPA gene." (PMID 38544400, 2024). "Canavan disease (CD) is an ultra-rare autosomal recessive leukodystrophy caused by loss-of-function mutations in ASPA, which encodes aspartoacylase (ASPA), leading to accumulation of N-acetylaspartate (NAA)." (PMID 39628365, 2024). "These immune-evading OPCs were transplanted into the brain of a mouse model of Canavan disease, a lethal demyelinating disease caused by mutations in the aspartoacylase (ASPA) gene." (PMID 38397466, 2024). "Canavan disease is a recessively inherited early onset leukodystrophy caused by inactivating ASPA mutations that diminish oligodendroglial aspartoacylase activity." (PMID 38282243, 2024). "With the obvious diagnostic value for Canavan disease, much work has been put into assays to determine ASPA enzymatic activity." (PMID 38582917, 2024). "Canavan disease (CD) is a devastating leukodystrophy starting in early life, caused by mutations in the ASPA gene." (PMID 39682723, 2024). "Astroglial conditional Slc13a3 deletion in aspartoacylase‐deficient Canavan disease model mice (“CD mice”) reversed brain NAA elevation and improved motor function." (PMID 38282243, 2024). "Canavan disease is a type of leukodystrophy arising from harmful aspartoacylase (ASPA) gene mutations." (PMID 39156766, 2024). "Canavan disease is an autosomal recessive disorder caused by loss‐of‐function mutations in the ASPA gene." (PMID 38544400, 2024). "Canavan disease (CD), due to homozygous mutations of aspartoacylase (ASPA), is to our knowledge the only primary oligodendrogliopathy where the primum movens of the pathology is undisputably located in OLs." (PMID 39682723, 2024). "Insufficient ASPA activity caused by germline ASPA variants is linked to Canavan disease (CD) (OMIM: 271900), a recessive, neurodegenerative leukodystrophy, where oligodendrocytes fail to correctly myelinate neuroaxons." (PMID 38582917, 2024). "Canavan disease (CD) is a rare genetic disorder resulting from autosomal recessive mutations in the aspartoacylase (ASPA) gene, leading to deficient breakdown of N-acetylaspartic acid (NAA) within the brain." (PMID 39559557, 2024). "Canavan disease (CD) is a lethal demyelinating disease caused by mutation of the aspartoacylase (ASPA) gene, which leads to the accumulation of its substrate N-acetyl-l-aspartate (NAA), and consequently demyelination and vacuolation in the brain." (PMID 37271923, 2023). "Canavan disease is induced by mutations in ASPA, which significantly increase the concentration of NAA in the brain." (PMID 37391709, 2023). "Canavan disease: Canavan disease is due to a deficiency of aspartoacylase, which catalyzes the hydrolysis of NAA and leads to accumulation of NAA." (PMID 35453911, 2022). "The leukodystrophy Canavan disease is a fatal white matter disorder caused by loss-of-function mutations of the aspartoacylase-encoding ASPA gene." (PMID 36568275, 2022). "Canavan disease shows spongy vacuolation of subcortical white matter due to a defective gene encoding aspartoacylase, which is particularly enriched in oligodendrocytes." (PMID 36348444, 2022).
Canavan disease (continued). "Our focus in the present study is on the C152W variant, which has been associated with loss of ASPA activity in vitro and accordingly Canavan disease." (PMID 33914734, 2021). "Canavan disease is a fatal neurodegenerative disorder which is genetically linked to polymorphisms in the aspartoacylase (ASPA) gene." (PMID 33914734, 2021). "Within the ASPA gene, more than 50 variants have been linked to Canavan disease, primarily consisting of single nucleotide substitutions." (PMID 33914734, 2021). "Canavan Disease (CD) is an autosomal recessive disorder (MIM# 608034) caused by mutations in the aspartoacylase (ASPA) gene, encoding the ASPA enzyme that hydrolyzes N-acetyl-L-aspartic acid (NAA) to aspartate and acetate in oligodendrocytes." (PMID 35096710, 2021). "The mechanism linking loss of ASPA function to the phenotypes associated with Canavan disease is still debated." (PMID 33914734, 2021). "A hereditary genetic mutation of the gene coding for ASPA is known as Canavan Disease (CD), causing the loss of ASPA activity." (PMID 33809224, 2021). "Canavan disease is a spongiform leukodystrophy caused by loss-of function mutations in the oligodendroglia aspartoacetylase (ASPA) encoding gene." (PMID 34239416, 2021). "Pathologically elevated NAA with associated loss of ASPA activity is the primary diagnostic hallmark of Canavan disease." (PMID 33614826, 2021). "Canavan disease (CD) is a fatal leukodystrophy caused by mutation of the aspartoacylase (ASPA) gene, which leads to deficiency in ASPA activity, accumulation of the substrate N‐acetyl‐L‐aspartate (NAA), demyelination, and spongy degeneration of the brain." (PMID 33304759, 2020). "The extreme of this phenomenon would be Canavan disease, an autosomal-recessive mutation of the aspartoacylase gene associated with severe neurodegeneration." (PMID 32362872, 2020). "Toxic NAA accumulation appears to be the key factor for neurological decline in Canavan disease—a fatal neurometabolic disorder caused by deficiency in the NAA-degrading enzyme aspartoacylase." (PMID 29116375, 2018). "Mutations in ASPA are associated with Canavan disease (OMIM 271900), a leukodystrophy that presents in the first year of life with delayed psychomotor development, hypotonia, macrocephaly, and epilepsy after an initially normal development." (PMID 29453510, 2018). "Mutations in the ASPA gene result in Canavan disease, which leads to hypomyelination, severe developmental delay, brain vacuolization and early death." (PMID 28626388, 2017). "A recent study has indicated that even low levels of residual ASPA activity associated with certain ASPA mutations result in milder forms of Canavan disease." (PMID 28626388, 2017). "Canavan disease is caused by mutations in the gene encoding aspartoacylase (ASPA), a deacetylase that catabolizes N-acetylaspartate (NAA)." (PMID 28626388, 2017). "The importance of ASPA to myelination is highlighted by the severely dys-myelinated phenotype of the inherited human paediatric leukodystrophy, Canavan disease (CD), which results from the loss of ASPA function." (PMID 27394419, 2017). "We describe 14 patients with 12 novel missense mutations in ASPA, the gene causing Canavan disease (CD)." (PMID 28101991, 2017). "Canavan disease is a neurodegenerative disease caused by deficiency in aspartoacylase (ASPA; Hoshino and Kubota, 2014)." (PMID 27655972, 2016). "These lesions attributed to alterations in the oligodendrocytes are also seen in a model of leukoencephalopathy resulting from disruption of the chloride channel ClC-2 and in the Nur7 aspartoacylase-deficient mouse model of Canavan disease." (PMID 25763823, 2015). "Canavan Disease (CD) is a leukodystrophy caused by homozygous null mutations in the gene encoding aspartoacylase (ASPA)." (PMID 24826990, 2014). "Canavan disease is a leukodystrophy – a disease characterized by degeneration of white matter of the brain – that is caused by recessive mutations in the ASPA gene." (PMID 24682784, 2014).
Canavan disease (continued). "Canavan disease is a rare form of leukodystrophy caused by a deficiency of aspartoacylase — an enzyme hydrolyzing NAA to acetate and aspartate." (PMID 24892353, 2014). "The short chain triglyceride glyceryl triacetate (GTA), which increases histone acetylation and inhibits histone deacetylase expression, has been safely used for acetate supplementation in Canavan disease, a leukodystrophy due to ASPA mutation." (PMID 24278309, 2013). "For example, mutations in the human aspartoacylase gene, which is flanked by an olfactory receptor rich-region on chromosome 17p13.3, cause Canavan disease." (PMID 21390308, 2011). "Canavan Disease (CD) is a recessive leukodystrophy caused by loss of function mutations in the gene encoding aspartoacylase (ASPA), an oligodendrocyte-enriched enzyme that hydrolyses N-acetylaspartate (NAA) to acetate and aspartate." (PMID 21625469, 2011). "Increased levels of NAA represent a typical feature of Canavan Disease, a fatal dysmyelinating disorder caused by mutations of the oligodendrocytic enzyme aspartoacylase (ASPA)." (PMID 21750683, 2011). "The aspartoacylase (Aspa) mutation in nur07 (Q193X) represents a model of human Canavan disease, a progressive disorder of myelination." (PMID 20011118, 2009). "One individual was found to carry a 12 kb deletion in one copy of the ASPA gene on 17p13, which when mutated in both alleles leads to Canavan disease." (PMID 18925931, 2008). "In human medicine, spongy leukodystrophy (also known as Canavan disease) is characterized by diffuse symmetrical WM spongy degeneration with prominent early involvement of subcortical U fibers and is caused by mutations in the aspartoacylase (ASPA) gene." (PMID 38544400, 2024). "Thus, Canavan disease was characterized as a monogenic disease, caused by insufficient aspartoacylase activity leading to loss of NAA catabolism." (PMID 38582917, 2024). "Canavan disease is a leukodystrophy caused by ASPA mutations that diminish oligodendroglial aspartoacylase activity, and is characterized by markedly elevated brain concentrations of the aspartoacylase substrate N‐acetyl‐l‐aspartate (NAA) and by astroglial and intramyelinic vacuolation." (PMID 38282243, 2024). "Canavan disease (CD) is a rare leukodystrophy stemming from the loss of function in the aspartoacylase (ASPA) gene within modified ASPA-expressing mature oligodendrocytes of the central nervous system (CNS) and characterized by macrocephaly, neurodevelopmental delays, and tone abnormalities." (PMID 38727281, 2024). "At the molecular level, recent studies have shown that most disease linked ASPA gene variants lead to a structural destabilization and subsequent proteasomal degradation of the ASPA protein variants, and accordingly Canavan disease should in general be considered a protein misfolding disorder." (PMID 38582917, 2024). "Canavan disease results from a mutation in the gene encoding aspartoacylase (ASPA)." (PMID 36003149, 2022). "Loss of enzymatic activity in aspartoacylase (ASPA) is tightly linked to Canavan disease." (PMID 33914734, 2021). "Canavan disease (CD) is a leukodystrophy caused by mutation of the aspartoacylase(ASPA) gene." (PMID 33304759, 2020). "The ASPA gene encodes for aspartoacylase enzyme, deficiency of which results in Canavan disease." (PMID 33138774, 2020). "Thus, the impact of NAA metabolism is illustrated by the brain damages associated with the NAA catabolic enzyme called aspartoacylase in Canavan disease, an early-onset spongiform leukodystrophy." (PMID 30180851, 2018). "Canavan disease is a leukodystrophy caused by mutations in the ASPA gene." (PMID 24682784, 2014). "Canavan disease is caused by loss-of-function mutations in the gene encoding aspartoacylase." (PMID 24682784, 2014). "In addition, the abundance of NAA in the urine is a marker for Canavan disease (CD), which is a leukodystrophy caused by deficiency of the enzyme aspartoacylase." (PMID 20830293, 2010).
Canavan disease (continued). "Mutations of ASPA gene cause Canavan disease [MIM608034], an autosomal recessive disorder." (PMID 18925931, 2008). "The enzyme known as aspartoacylase (ASPA), which is found in the cytosol, catalyses the breakdown of n-acetylaspartate into aspartate and acetic acid, with the ASPA mutations leading to substantial increases in N-acetylaspartic acid concentrations in the brain, resulting in Canavan disease." (PMID 37391709, 2023). "Here we present systematic studies of the cytosolic aspartoacylase, ASPA, where variants are linked to Canavan disease, a lethal neurological disorder." (PMID 38740822, 2024). "iPSC-based cell therapy was developed for Canavan disease by introducing the aspartoacylase (ASPA) gene into patient iPSC-derived neural progenitor cells or oligodendrocyte progenitor cells using TALEN-mediated genetic engineering." (PMID 34887928, 2021). "In contrast, elimination of aspartoacylase expression exclusively in oligodendrocytes elicited Canavan disease like pathology." (PMID 29116375, 2018). "ASPA catalyzes conversion of N-acetyl-L-aspartic acid (NAA) to acetate and is mutated in patients with Canavan disease." (PMID 28245795, 2017). "Subsequently it was discovered that mutations in the gene for the enzyme that deacetylates NAA, known as aspartoacylase or ASPA, lead to the fatal neurodegenerative disorder known as Canavan disease." (PMID 24421768, 2013). "Canavan disease (CD, OMIM # 271900) is an autosomal recessive inherited metabolic disease caused by biallelic pathogenic variants in ASPA that lead to a deficiency of the enzyme aspartoacylase (ASPA) (OMIM * 608034)." (PMID 40257001, 2025). "Defects in ASPA functionality leads to Canavan disease (MIM# 271900), a type of leukodystrophy." (PMID 38582917, 2024). "Although the PQC system is highly conserved across species, yeast—which does not encode any orthologue of ASPA—is obviously an artificial system to analyze the PQC system of relevance for Canavan disease." (PMID 38740822, 2024). "If, however, an E3 important for ASPA degradation could be identified, it could potentially be a promising therapeutic target for Canavan disease." (PMID 33914734, 2021). "A recent study has modified induced neural progenitor cells (NPCs) and induced oligodendroglial progenitor cells (OPCs) from Canavan disease (CD) patients to express human aspartoacylase (ASPA) via lentivirus mediated gene addition and TALEN mediated gene editing." (PMID 34239416, 2021). "However, comparable endpoints of the conditional and complete aspartoacylase knockout indicate that optimal Canavan disease gene replacement therapies should restore aspartoacylase expression in oligodendrocytes." (PMID 29116375, 2018). "Conversely, lack of NAA catabolism caused by missense mutations in the ASPA gene results in the leukodystrophy Canavan disease (CD) characterized by a build-up of NAA in brain, blood and urine." (PMID 29116375, 2018). "Because Myo1d has been reported to interact with ASPA in vitro and colocalizes with ASPA in brain, Myo1d may also be related to Canavan disease, a fatal neurological disorder that results in the deterioration of myelin." (PMID 27655972, 2016). "The lack of the enzyme aspartoacylase (ASPA) causes the fatal leukodystrophy Canavan disease (CD)." (PMID 24826990, 2014). "Here we comprehensively summarize the physiological, cellular, and molecular details of the ASPA enzyme, its substrate NAA and Canavan disease." (PMID 38582917, 2024). "In Canavan disease where ASPA activity is absent and NAA levels are high, histone H3 acetylation is increased in oligodendrocytes, including at loci such as H3K9." (PMID 33304273, 2020). "Two human inborn errors are related to NAA metabolism: Canavan disease in which there is a buildup of NAA and associated spongiform leukodystrophy, caused by a lack of aspartoacylase activity." (PMID 31076607, 2019).
Canavan disease (continued). "By way of positional cloning techniques, the tremor rat model (tm/tm) was constructed by genomic deletion in the region containing the ASPA gene, resulting in lack of ASPA expression and presence of phenotypical Canavan disease traits such as CNS spongiform degeneration." (PMID 33967698, 2021). "Interestingly, it has also been shown that the enzymatic activity of ASPA in four non-affected, heterozygous carrier parents of Canavan disease patients was 40% of the WT ASPA, further compounding efforts to properly correlate the genotypic and phenotypic relationship in Canavan disease." (PMID 33967698, 2021). "In Canavan disease, the increase in NAA is due to the absence of the enzyme aspartoacylase which is responsible for breaking down NAA." (PMID 40503083, 2025).